LAG3 (lymphocyte activating 3)
Diseases named in the same sentence as LAG3 in open-access papers (continued):
Sharing a sentence is not in itself a finding about the gene and the disease.
breast cancer (continued). "Moreover, predicting the role of LAG3 in breast cancer and pancreatic ductal adenocarcinoma prognosis is controversial, and we believe that the discrepancy between these two tumors can be attributed to tumor heterogeneity." (PMID 35111155, 2021). "PD-1+/LAG-3+ expression was associated with a “hot” immune phenotype both in PBTs and METs regardless of the breast cancer molecular subtype." (PMID 33413541, 2021). "The prognostic value of LAG3 in breast cancer is controversial." (PMID 35111155, 2021). "LAG3 expression was closely related to the malignancy of breast cancer and may serve as a potential biomarker." (PMID 34267742, 2021). "Anti-LAG-3 treatment was also found to restrict breast carcinoma growth in an animal model." (PMID 34454491, 2021). "To determine whether these combined predictors of cancer prognosis were applicable in breast cancer, we additionally examined the expression of PD-1, PD-L1, TIGIT, TIM3, and LAG3 in breast cancer tissue microarrays." (PMID 33250890, 2020). "Interestingly, and in contrast to these findings, recent studies in breast cancer patients showed a favourable outcome in LAG3 positive tumours regarding the overall survival (OS) of the patients, while other studies showed a worse prognosis in breast cancer." (PMID 32592066, 2020). "Our data suggests that LAG-3 may play an important role in breast cancer skin metastases as well and LAG-3 inhibition and PD-1 inhibition should be considered in combination with imiquimod as possible treatment modalities." (PMID 31189943, 2019). "Moreover, despite the emergence of distinct Breg subtypes in malignant neoplasias, to the best of our knowledge, here we reported for the first time the dynamic of B10 and, most importantly, LAG-3 + B cells under physiological, basal-like, and claudin-low breast cancer subtypes." (PMID 38773133, 2024). "Likewise, a strong PD-1 and LAG-3 relation in the breast cancer patients was observed." (PMID 37174080, 2023). "Nowadays, inhibitors of LAG-3 are investigating in clinical trials to treat other types of malignancies like breast cancer; evidences appeared to be promising due to survival rate of 50%, which might provide consistent rationale to apply this strategy for mesothelioma treatment as well." (PMID 35785199, 2022). "In addition to PD-1 and PD-L1, further immune checkpoints, such as LAG-3, could serve as therapeutic targets in breast cancer." (PMID 36289918, 2022). "Furthermore, analysis of metastatic breast cancer tissue may improve the stratification of advanced breast cancer patients for a dual anti-PD-1/anti-LAG-3 immunotherapy." (PMID 33413541, 2021). "LAG-3-expressing tumors are usually associated with poor survival, although a high expression of LAG-3 is associated with favorable overall survival and disease-free survival in some solid tumors, particularly in early-stages, such as breast cancer, ENKTL nasal type, NSCLC, and TNBC." (PMID 34067904, 2021). "The main immune checkpoints for breast cancer include cytotoxic T-lymphocyte-associated protein-4 (CTLA-4), programmed death receptor 1/programmed cell death ligand 1 (PD-1/L1), lymphocyte activation gene 3 (LAG-3), T cell immunoglobulin domain and mucin 3 (TIM-3) and other molecules." (PMID 34631507, 2021). "We found that breast cancer cells upregulate the expression of ICs including PD-1, cytotoxic T lymphocyte-associated antigen-4 (CTLA-4), T cell immunoglobulin and mucin domain-containing protein 3 (TIM-3) and lymphocyte activation gene-3 (LAG-3) in CD4+ T cell subsets." (PMID 31614877, 2019). "Pretreatment tumor biopsies from 166 patients with early breast cancer treated with standard NACT were assessed for stromal TILs and mRNA expression of CD8, PD-1, LAG-3, and TIM-3." (PMID 41828646, 2026). "FGL1, a Ligand of lymphocyte-activation gene 3 (LAG3), also known as hepassocin, HRFREP-1, and FREP1, is primarily expressed on the surface and within the cytoplasm of lung and breast cancer cells." (PMID 41024301, 2025).
breast cancer (continued). "Like breast cancer, ESCC is another tumor type where high LAG3 expression is either positively correlated with better prognosis or shows no clear association." (PMID 40411616, 2025). "In breast cancer, a decrement of H3K9me3 modification was reported on promoters of key immune checkpoints, namely PD-1, CTLA-4, and lymphocyte activating 3 (LAG-3)." (PMID 39519018, 2024). "In inflamed cancer types including breast cancer, NcDase expression correlated strongly with the expression of the markers of immune regulation (CTLA4, LAG3, PDCD1, SIGLEC15)." (PMID 38302493, 2024). "We have also explored the GDC TCGA Breast Cancer (BRCA) dataset on the UCSC Xena browser, and our preliminary findings show that LAG-3 is indeed hypermethylated in its promoter region in contrast to the FGL1 promoter." (PMID 39796650, 2024). "LAG3 showed a protective effect in AML, ovarian cancer, and breast cancer, while in bladder cancer (transitional cell carcinoma) and breast and brain cancer (glioma), it presented an adverse prognostic role." (PMID 39064019, 2024). "In early-stage breast cancer, high co-expression of TIGIT and other immune checkpoint receptors—including PD-1, CTLA-4, LAG-3, and TIM-3—on tumor-infiltrating lymphocytes correlates with increased disease aggressiveness." (PMID 39717767, 2024). "The results showed that in breast cancer, GPS1 expression was positively correlated with LAG3, PVRL2, and LGALS9, and negatively correlated with CD274 and HAVCR2, but not with CTLA4 and PDCD1." (PMID 38289496, 2024). "LAG3 is upregulated in breast cancer tissues, especially enriched in HER2-positive patients and those with high tumor grade, indicating that high expression of LAG3 is indicative of highly malignant breast cancer." (PMID 38289496, 2024). "The analysis revealed that the PD-1, LAG-3 and TIM-3 gene expression differed between the breast cancer subtypes." (PMID 37174080, 2023). "Its expression has been demonstrated to be downregulated with repeated antigen stimulation, while PD-1 and LAG3 remained high and TIM-3 increased further in T cells from a murine breast cancer model." (PMID 38023136, 2023). "This molecular phenotype suggests a relationship between the CD103+LAG3+CD8+ T-cell subset and improved prognosis of breast cancer patients." (PMID 37488535, 2023). "Moreover, RAPA-201 therapy, which has been thought to block the expression of PD-1, CTLA-4, TIM-3, and LAG3, thereby improving the immune suppressive tumor microenvironment, is currently being trialed in a phase I/II study for patients with solid cancer (including breast cancer) (NCT05144698)." (PMID 36765782, 2023). "Nevertheless, we reached similar conclusions in the higher LAG-3 expression in more advanced stages, grades, and types (TNBC) of breast cancer." (PMID 37264298, 2023). "Based on the expression profiles of marker genes in these two subpopulations, we further developed a CD103+LAG3+ TIL-related prognostic model (CLTRP) based on CXCL13 and BIRC3 genes for predicting the prognosis of breast cancer patients." (PMID 37488535, 2023). "Combination of LAG3 ICB with antiPD-1 therapy has shown synergistic effects, reducing tumor growth and increasing survival in breast cancer-bearing mice also treated with a dendritic cell vaccine." (PMID 36831412, 2023). "The soluble form of LAG-3 was detectable only in small amounts in the HTM, although elevated LAG-3 expression was found on the CD4 and CD8 T cells in the MDA-MB-231 HTM and PDX model as well as in the dataset of breast cancer patient samples." (PMID 37174080, 2023). "In breast cancer cells, MHC class II expression confers response to ICI, using either combination therapy with anti-PD-1 and anti-Lag-3 or treatment with anti-CTLA-4." (PMID 35565329, 2022). "FGL1 is a ligand of the lymphocyte-activation gene 3 (LAG3), which is mainly expressed on the surface and cytoplasm of lung and breast cancer cells, and is believed to prevent the activation of T cells." (PMID 36268014, 2022).
breast cancer (continued). "We recently reported that the new generation ICRs TIM-3, LAG-3, and TIGIT are highly expressed in locally advanced breast cancer with poor prognostic factors following neoadjuvant chemotherapy." (PMID 36271406, 2022). "On immune checkpoint genes in breast cancers, POGLUT2 was positively correlated with CTLA4, CD274, TIGIT, LAG3, and PDCD1." (PMID 36158688, 2022). "EOC202 is a recombinant human LAG-3 fusion protein injection combined with albumin-bound paclitaxel for the treatment of patients with HR+, HER2- advanced breast cancer with progression after endocrine therapy (NCT05322720)." (PMID 35954196, 2022). "It has also been examined the levels and prognostic values of 50 ICR genes in molecular subgroups of breast cancer, including PD-1, CTLA-4, TIGIT, LAG-3, and TIM-3." (PMID 36271406, 2022). "Our study shows that DNT cells from healthy donors expressed LAG3, and breast cancer cells expressed MHC II, which is also the main ligand of LAG3, suggesting that LAG3 makes a high contribution to the cytotoxicity of DNT cells to breast cancer." (PMID 35894707, 2022). "The main immune checkpoints for breast cancer include CTLA-4, PD-1/PD-L1, lymphocyte activation gene 3 (LAG-3), T-cell immunoglobulin domain and mucin 3 (TIM-3), and other molecules." (PMID 35603151, 2022). "In the present, retrospective, gene-expression study, we demonstrated that LAG-3, as a next generation ICP, has independent prognostic significance in terms of MFS in a cohort of 461 breast cancer patients with long-term follow up." (PMID 36289918, 2022). "LAG3 is expressed in various tumors, such as KIRC, gastric cancer, breast cancer, B-cell lymphoma, and lung cancer." (PMID 35111155, 2021). "However, some studies arrived at the seemingly opposite conclusion that high expression of LAG3 is associated with favorable overall survival of patients with solid tumors including ovarian, gastric, lymphoma, NSCLC, colorectal, and renal, as well as breast cancer." (PMID 34267742, 2021). "A dual blockade against the novel immune checkpoint inhibitor lymphocyte activation gene-3 (LAG-3) and programmed cell death protein-1 (PD-1) is currently considered in advanced breast cancer." (PMID 33413541, 2021). "Examples of immune targets under investigation for the treatment of specific breast cancer subtypes include B7-H3, LAG3 and CTLA4; there is also interest in assessing the role of Bcl-2 inhibition in selected patients with breast cancer." (PMID 34838031, 2021). "Several studies have addressed the beneficial usage of anti-LAG3 therapy in different malignancies: one monoclonal anti-LAG3 antibody, IMP321, was able to activate antigen-presenting cells (APCs) and T cells in breast cancer." (PMID 34503258, 2021). "Lymphocyte-activation gene 3 (LAG-3) and T-cell Ig and mucin domain-containing protein 3 (TIM-3) are also attractive immunosuppressive targets being actively investigated in breast cancer." (PMID 33256070, 2020). "In this study, the expression patterns of immune checkpoints, such as PD-1, CTLA-4, TIGIT, and LAG3, are quite different from that of VISTA in breast cancer microenvironment." (PMID 33250890, 2020). "We also analyzed the expression characters of other immune checkpoints such as PD-1, PD-L1, TIM3, LAG3, and TIGIT in breast cancer tissue." (PMID 33250890, 2020). "Collectively, we found that breast cancer cells upregulated the expression of PD-1, CTLA-4, TIM-3 and LAG-3 in the different subsets of CD4+ T cells." (PMID 31614877, 2019). "We determined the kinetics and level of expression of key inhibitory ICs (PD-1, CTLA-4, TIM-3 and LAG-3) and Treg-related markers (FoxP3 and Helios) in CD4+ T cells in the absence or presence of breast cancer cells." (PMID 31614877, 2019). "Additionally, BRCA1/2-deficient breast cancers have a higher expression of immunosuppressive molecules compared with BRCA1-WT breast cancers in WSI and TCGA cohorts, including CTLA-4, IDO1, and LAG3." (PMID 40830526, 2025).
breast cancer (continued). "As an immunotherapeutic target currently under investigation, the correlation between LAG3 and GPS1 may provide new ideas for effective immunotherapy of breast cancer." (PMID 38289496, 2024). "Nevertheless, although LAG-3 blockade as monotherapy does not result in increased NK cell-mediated cytotoxicity, combination with IL-12 in murine models of breast cancer restored the antimetastatic activity of this immune subset." (PMID 39425148, 2024). "Comparison of the plasma concentrations of the soluble co-inhibitory immune checkpoints, PD-L1, LAG-3 and TIM-3 and the soluble dual-activity checkpoint, HVEM, measured in the group of healthy control subjects and the cohort of early breast cancer patients post-neoadjuvant chemotherapy (NAC)." (PMID 37064132, 2023). "In another study, LAG3 (lymphocyte activating gene 3-IgG) and P5 peptide were coupled into the surface of PEGylated liposomes for simultaneous co-delivery and were investigated for their therapeutic effectiveness in a mice model of TUBO breast cancer." (PMID 36992244, 2023). "Overexpression of LAG3 is found in many types of human tumors such as CRC, breast cancer, liver carcinoma, follicular lymphoma, and squamous cell carcinoma of the head and neck, and in most cases, is significantly correlated with the development of an invasive tumor and worse outcome." (PMID 36765348, 2023). "A study that specifically included breast cancer patients was a phase I study of LAG525, a monoclonal antibody blocking the binding of LAG-3 to MHC-II in combination with spartalizumab (an anti-PD-1 antibody) in patients with advanced malignancies, which showed durable responses." (PMID 38263984, 2023). "Recently, the LAG3 antibody relatlimab has been approved by the FDA for the treatment of resistant melanoma, evidencing the safety of the therapy and offering hope for the treatment of resistant breast cancers." (PMID 36831412, 2023). "Analysis of a dataset containing 3039 primary breast cancer samples on the R2 Genomics Analysis Platform revealed increased TIM-3, galectin-9 and LAG-3 expression, not only in triple-negative breast cancer but also in the HER2+ and hormone receptor-positive breast cancer subtypes." (PMID 37174080, 2023). "According to the phase II I-SPY2 trial (NCT01042379), the combination of cemiplimab and a lymphocyte activation gene-3 (LAG-3) inhibitor, fianlimab along with paclitaxel exhibited a significant pathologic complete response than paclitaxel alone in HR + and HER2 − breast cancer or TNBC patients." (PMID 37415164, 2023). "Interestingly, in cats with mammary carcinoma, our results revealed a positive correlation between the TIM-3 and the LAG-3 serum levels (p = 0.008)." (PMID 36672332, 2023). "Considering our previous results showing that cats with mammary carcinoma have higher circulating levels of several immunomodulatory molecules (IL-6, TNF-α, CTLA-4, PD-1, PD-L1, VEGF-A, VEGFR-1, VEGFR-2, and LAG-3), the serum TIM-3 levels were evaluated to check for statistical correlations." (PMID 36672332, 2023). "Moreover, the expression of LAG3, CTLA-4, PD-L1, CD274, TIGIT, HAVCR2 and PDCD1LG2 was upregulated in the TFRC high-expression group compared with the TFRC low-expression group in breast cancer." (PMID 35847985, 2022). "Findings suggest that the double-positive expression of LAG-3 and PD-1 predicts for a negative prognosis in breast cancer patients, affecting shortened disease-free survival, especially in patients with metastases." (PMID 36077354, 2022). "In estrogen receptor-negative breast cancers LAG-3+ iTILs demonstrated higher expression and were correlated with negative prognostic factors: young age, large tumor size, high proliferation, HER2E and basal-like breast cancer subtypes." (PMID 36077354, 2022). "In Luminal B, the high expression of LAG3 represents a good prognosis, while LAG3 expression was not significantly relevant to the prognosis of other subtypes of breast cancer." (PMID 35894707, 2022).
breast cancer (continued). "LAG3 and PD1 double positive expression is evident either in triple negative breast cancer (TNBC), or in estrogen receptor+/progesterone receptor +(ER+/PR+ breast cancer." (PMID 35111155, 2021). "Although LAG-3 blockade, along with IL-12 treatment, was shown to restore the anti-metastatic activity of NK cells in murine models of breast cancer, relatlimab did not directly induce NK cell-mediated cytotoxicity against leukemic cells." (PMID 33925565, 2021). "The results showed that the predictive scores had a significant positive correlation with the immune checkpoints, such as PD1, PD1L2, and was particularly highly correlated with CTLA4, LAG3, and IDO1, suggesting immune regulation plays a key role in the prognosis of breast cancer chemotherapy." (PMID 34526986, 2021). "Finally, we performed immunohistochemistry with breast cancer tissue samples and observed that CXCL9 is highly expressed in the ER-negative subgroup and positively correlated with the immune-related factors LAG3, PD1, PDL1 and CTLA4 to varying degrees." (PMID 34527583, 2021). "LAG3 is likely predominantly expressed in immune cell populations in the tumor microenvironment, but not by breast cancer cells." (PMID 34267742, 2021). "Again PD-1+/LAG-3+ expression correlated to “hot” brain METs regardless of the molecular breast cancer subtype supporting our previous notion of a tumor intrinsic immunogenicity." (PMID 33413541, 2021). "Other novel immunological breast cancer (BrCa) targets, such as T-cell immunoglobulin and mucin domain-containing molecule 3 (TIM-3) and lymphocyte activation gene 3 (LAG-3), may yield additional prognostic information in TNBCs." (PMID 34039396, 2021). "The co-expression of LAG3 and PD1 or PD ligand 1 (PD-L1) has been proven in breast cancer." (PMID 35111155, 2021). "To address this knowledge gap, we investigated the PD-1 and LAG-3 expression in combination with the CD8-based immune phenotype in intrapatient matched primary tumor distant metastases, representing 95 breast cancer patients with metastases occurring at four different anatomical locations." (PMID 33413541, 2021). "Moreover, the amount of LAG3+PD1+ T cells is different in various molecular subtypes of breast cancer, with the highest being in TNBC and lowest in ER+/PR+ breast cancer." (PMID 35111155, 2021). "Interestingly, we found that PD‐L1 and LAG3 were highly positive related to IDO1 in gynaecologic and breast cancers, but their correlation was reduced in normal breast tissue, ovary and uterus/cervix." (PMID 32227579, 2020). "Increased TILs were described with reduced proliferative suppression in neoadjuvant, endocrine-treated, postmenopausal, ER+ breast cancer with increased levels of immune checkpoint components IDO1, PD-1 and LAG3 described with AI-resistant proliferation in luminal B cancer." (PMID 32825588, 2020). "Importantly, implantation of murine mammary tumor cells during post-partum mammary gland involution elicits a CD8+ T cell population that expresses both the co-inhibitory receptors PD-1 and Lag-3." (PMID 31244852, 2019). "Unlike the blockade of PD-L1, anti-PD-1 alone did not further upregulate TIM-3 and LAG-3 co-expression on CD4+CD25+FoxP3+Helios+ Tregs in the presence of breast cancer cells." (PMID 31614877, 2019). "Moreover, high LAG-3 expression has been found in an extensive range of tumors including NSCLC, gastric cancer, colorectal cancer, breast cancer, ovarian cancer, HCC, RCC, FL, HNSCC, prostate cancer, pancreatic cancer, anal squamous cell carcinoma, and malignant pleural mesothelioma." (PMID 37509517, 2023). "Multicolor immunophenotyping was used to determine the expression of PD‐1, TIM‐3, LAG3, CTLA‐4, CCR7, CD45RO, CD127, CD25, CXCR5, and ICOS molecules on CD3+CD4−CD56−CD8+ cytotoxic T cells freshly obtained from the lymph nodes and the peripheral blood samples of the breast cancer patients." (PMID 38069525, 2023).